ZNF699 (zinc finger protein 699)
Description:
May be involved in transcriptional regulation.
Synonyms: FLJ38144; DEGCAGS; hang
Tractability: PROTAC: ubiquitination databases record sites on it.
Gene: Protein-coding gene on chromosome 19 (9,291,140 to 9,309,838, reverse strand). Ensembl gene ENSG00000196110.
Subcellular location: Nucleus
Pathways (Reactome):
Gene expression (Transcription): Generic Transcription Pathway
Gene Ontology:
Molecular function: protein binding; DNA-binding transcription factor activity, RNA polymerase II-specific; RNA polymerase II cis-regulatory region sequence-specific DNA binding
Biological process: regulation of transcription by RNA polymerase II; regulation of DNA-templated transcription
Cellular component: nucleus
Genetic constraint (gnomAD): Loss-of-function variants: 21 observed, 21.38 expected, observed/expected ratio (o/e) 0.98, 90% interval 0.7 to 1.41. The upper end of that interval is the gene's LOEUF score, 1.41, which puts it in group 5 of 6, group 1 being the genes least tolerant of losing a copy. Missense variants: 659 observed, 787.29 expected, observed/expected ratio (o/e) 0.84, 90% interval 0.78 to 0.89. Synonymous variants: 238 observed, 270.8 expected, observed/expected ratio (o/e) 0.88, 90% interval 0.79 to 0.98.
Homologues: Orthologues: chimpanzee ZNF699 (99% identical), macaque ZNF699 (90% identical), dog ZNF699 (82% identical), guinea pig ZNF699 (78% identical), rabbit ZNF699 (77% identical). Paralogues in human: ZNF568 (44% identical), ZNF658 (44% identical), ZNF33B (44% identical), ZNF595 (44% identical), ZNF546 (43% identical), ZNF606 (43% identical), ZNF470 (43% identical), ZNF724 (43% identical), ZNF717 (42% identical), ZNF726 (42% identical), ZNF585B (42% identical), ZNF30 (42% identical), and 164 more.
Diseases named in the same sentence as ZNF699 in open-access papers:
ZNF699 is named in the same sentence as 7 diseases in open-access papers, as found by Europe PMC text mining. Sharing a sentence is not in itself a finding about the gene and the disease. The quoted sentences say what the papers report.
alcohol dependence (2 papers, 2021 to 2022). Physical and psychological dependence on alcohol. "There were only two studies exploring the associations between variants in ZNF699 and alcohol dependence." (PMID 35205213, 2022).
developmental delay (1 paper, 2023). "Our patient was found to be homozygous for a novel pathogenic missense variant in the ZNF699 zinc‐finger gene on chromosome 19p13 causing a syndrome known as developmental delay with gastrointestinal, cardiovascular, genitourinary, and skeletal abnormalities syndrome." (PMID 38014480, 2023).
ZNF699 also shares sentences with these, for which no sentence is quoted: congenital heart defects (1 paper); connective tissue disorder (1); DEGCAGS syndrome (1); genetic disease (1); tumor (1).